TNNT2 (troponin T2, cardiac type)
Description:
Troponin T is the tropomyosin-binding subunit of troponin, the thin filament regulatory complex which confers calcium-sensitivity to striated muscle actomyosin ATPase activity.
Synonyms: TnTc; cTnT; CMPD2; CMD1D; CMH2; LVNC6; RCM3
Tractability: Small molecule: a drug acting on it is in phase 2 or 3 trials; a structure with a bound ligand is known; a high-quality ligand is known; it belongs to a druggable protein family. PROTAC: a small molecule that binds it is known.
Gene: Protein-coding gene on chromosome 1 (201,359,002 to 201,379,773, reverse strand). Ensembl gene ENSG00000118194.
Subcellular location (Human Protein Atlas): Nucleoli; Nucleoplasm; Focal adhesion sites; Microtubules
Pathways (Reactome):
Muscle contraction: Striated Muscle Contraction
Gene Ontology:
Molecular function: actin binding; protein binding; tropomyosin binding; troponin C binding; troponin I binding
Biological process: cardiac muscle contraction; muscle filament sliding; negative regulation of ATP-dependent activity; positive regulation of ATP-dependent activity; regulation of heart contraction; response to calcium ion; ventricular cardiac muscle tissue morphogenesis; sarcomere organization; regulation of muscle contraction; striated muscle contraction
Cellular component: cardiac myofibril; cardiac Troponin complex; striated muscle thin filament; troponin complex; cytosol; sarcomere
Genetic constraint (gnomAD): Loss-of-function variants: 31 observed, 61.22 expected, observed/expected ratio (o/e) 0.51, 90% interval 0.38 to 0.68. The upper end of that interval is the gene's LOEUF score, 0.68, which puts it in group 2 of 6, group 1 being the genes least tolerant of losing a copy. Missense variants: 274 observed, 390.41 expected, observed/expected ratio (o/e) 0.7, 90% interval 0.63 to 0.78. Synonymous variants: 123 observed, 133.16 expected, observed/expected ratio (o/e) 0.92, 90% interval 0.8 to 1.07.
Gene-disease validity (ClinGen):
ClinGen rates the evidence that TNNT2 causes each of these diseases.
dilated cardiomyopathy 1D (autosomal dominant): Definitive.
hypertrophic cardiomyopathy (autosomal dominant): Moderate. A condition in which the myocardium is hypertrophied without an obvious cause.
arrhythmogenic right ventricular cardiomyopathy (autosomal dominant): No Known Disease Relationship.
Homologues: Orthologues: chimpanzee TNNT2 (99% identical), macaque TNNT2 (99% identical), guinea pig TNNT2 (91% identical), pig TNNT2 (90% identical), mouse Tnnt2 (88% identical), rat Tnnt2 (88% identical), dog TNNT2 (86% identical), zebrafish tnnt2a (63% identical), tropical clawed frog tnnt2 (60% identical), zebrafish tnnt2b (49% identical), Caenorhabditis elegans tnt-3 (39% identical), Drosophila melanogaster up (33% identical). Paralogues in human: TNNT1 (56% identical), TNNT3 (54% identical).
Diseases named in the same sentence as TNNT2 in open-access papers:
TNNT2 is named in the same sentence as 307 diseases in open-access papers, as found by Europe PMC text mining. Sharing a sentence is not in itself a finding about the gene and the disease. The quoted sentences say what the papers report.
myocardial infarction (224 papers, 2010 to 2026). Gross necrosis of the myocardium, as a result of interruption of the blood supply to the area, as in coronary thrombosis. "Myocardial infarction remains one of the largest causes of death and although rapid ELISA tests against cardiac troponins TNNT2 and TNNI3 play a crucial role, further improvements in diagnosis would be of great clinical benefit." (PMID 29133944, 2017). "Our method successfully detected key myocardial infarction biomarkers, including TNNT2, FABPH, KCRM, L‐lactate dehydrogenase (A and B chain), and MYPC3." (PMID 40873137, 2025). "We found the elevated cardiac troponin expression (TNNT2, TNNI3, TTN) in cardiomyocytes across various CHD subtypes, suggesting increased myocardial stress and potential heart attack risk." (PMID 41010342, 2025). "We therefore incorporated a number of these biomarkers into a putative panel used to diagnose myocardial infarction: troponin T (TNNT2), fatty acid‐binding protein (FABPH), creatine kinase M type (KCRM), L‐lactate dehydrogenase (A and B chain), and cardiac myosin‐binding protein C3 (MYPC3)." (PMID 40873137, 2025). "TNNT2 was also found to be upregulated in cardiac hypertrophic or myocardial infarction conditions." (PMID 28866639, 2017). "The efficiency, accuracy, and perdurance of the Tnnt2 intronic RNAscope probe even with nuclear envelope breakdown facilitated reliable investigation of dynamics of DNA synthesis and potential mitoses in CMs in both border and infarct zones after myocardial infarction (MI)." (PMID 40195462, 2025). "Elevated blood levels of cardiac troponin (cTn), of the cTnI and cTnT subtypes (also known as TNNI3 and TNNT2, respectively), indicate cardiomyocyte injury and cell death, and are used in the clinic as an indicator of myocardial infarction." (PMID 39912384, 2025). "The troponin genes (TNNC1, TNNT2, TNNI3), the creatine kinase gene (CKM), and the brain natriuretic peptide gene (NPPA) are recognized biomarkers of myocardial infarction." (PMID 40433126, 2025). "Notably, JUP and VDAC3 exhibited a high correlation with myocardial infarction biomarkers; however, JUP also demonstrated a significant correlation with TNNC1, TNNT2, TNNI, CKM, and NPPA (P < 0.05)." (PMID 40433126, 2025).
heart failure (136 papers, 2008 to 2025). Inability of the heart to pump blood at an adequate rate to meet tissue metabolic requirements. "We identified a heterozygous in-frame deletion mutation (c.478_480del, p.Δ160E) in TNNT2 in a patient with familial hypertrophic cardiomyopathy showing progressive left ventricular systolic dysfunction, leading to advanced heart failure." (PMID 35861968, 2022). "We encountered a Japanese case of familial HCM with TNNT2 Δ160E mutation, who developed advanced heart failure with left ventricular systolic dysfunction > 20 years after the initial diagnosis of HCM." (PMID 35861968, 2022). "Altered Ca2+ cycling and cardiac contraction is well known in heart failure and was also demonstrated in iPSC-CMs with mutations causing defective sarcomere structures: S635A- in RBM20, E1680K in SPEG R173W in TNNT2." (PMID 37349842, 2023). "Molecular changes consistent with heart failure were evident by QPCR at age 50 weeks in Tnnt2+/−/TGK210Δ relative to Tnnt2+/−/TGWT mice." (PMID 18612386, 2008). "However, the ventricular walls appeared much thinner than those of Tnnt2+/+ and Tnnt2+/− embryos and large pericardial effusions suggested heart failure." (PMID 18612386, 2008). "Integrating the results of the TBX5-targeted genes and the DEGs in toxicity pathways, we found that the dysregulation of TBX5-targeted genes, TNNT2, NPPA, TTN, ATP2A2, DES and SCN5A, contributed to the development of heart failure and arrhythmia." (PMID 32423033, 2020). "Several proteins involved in heart failure were downregulated, which were found with the terms “Dilated cardiomyopathy” and “Cardiac muscle contraction”, such as TPM1 (Tropomyosin 1), TNNT2 (Troponin T2), ACTC1 (Actin, alpha, cardiac muscle 1)." (PMID 32165613, 2020). "Among the common DEGs between failure of heart and arrhythmia, DES and TNNT2 were among the top 50 DEGs." (PMID 32423033, 2020). "SFRP4, as the other activated upstream regulator, inhibited TNNT2 and MYH7, which contributed to the development of heart failure and arrhythmia." (PMID 32423033, 2020).
cardiomyopathy (87 papers, 2008 to 2026). A disease of the heart muscle or myocardium proper. "The TNNT2 gene is directly associated with various cardiomyopathies and is primarily expressed in heart muscle." (PMID 41345545, 2025). "Our labeled dataset contained 18 TNNT2 variants, of which 10 were benign and eight were pathogenic and causal for cardiomyopathy (OMIM #601494, #612422, and #115195)." (PMID 39285047, 2024). "For example, variants of the gene TNNT2 that were causal for cardiomyopathy were labeled as pathogenic in heart tissue and benign in other tissues." (PMID 39285047, 2024). "Of transcripts associated with cardiomyopathy, hypertrophy, and left ventricle alterations, Q‐PCR analysis was used to monitor the modulation of Ndufb7, Tnnt2, Ttn, Tnni3, and Plag2a." (PMID 37960940, 2023). "MYH7 and TNNT2 encode sarcomeric proteins, essential for contraction and relaxation of the heart muscle, and mutations in these genes have been linked to cardiomyopathy." (PMID 33172956, 2021). "In summary, this study suggests that the CELF4 (rs1786814) polymorphism modifies the dose-dependent association between anthracyclines and cardiomyopathy, possibly through pathways involving abnormal splicing of TNNT2 variants." (PMID 33110473, 2020). "We have identified a novel, homozygous mutation in the sarcomeric gene TNNT2, which is associated with cardiomyopathy in a Maine Coon cat." (PMID 33304277, 2020). "Cardiac muscle troponin T (Tnnt2) mediates muscle contraction in response to calcium ion dynamics, and Tnnt2 mutations are associated with multiple types of cardiomyopathy." (PMID 31796423, 2019). "Together, our results reveal the importance of OFT expression of Tnnt2 for cardiac function and indicate the complexity of assessing therapeutic strategies for cardiomyopathy caused by sarcomere-based mutations." (PMID 31796423, 2019). "One other issue with the cardiomyopathies reviewed by the AWG is that variants in TNNT2 can cause either dilated or hypertrophic cardiomyopathy." (PMID 30011878, 2018). "Nonetheless, a considerable number of variants in TNNT2, an important cardiomyopathy gene, were missed." (PMID 30022097, 2018). "We sought to repair a pathological mutation in Tnnt2 in cardiomyocytes of cardiomyopathy model mice." (PMID 28839205, 2017). "In conclusion, our findings suggest that the TNNT2 variant especially in combination with the BAG3 variant is associated with a high propensity to life-threatening cardiomyopathy presenting from childhood and young adulthood." (PMID 28669108, 2017). "Mutations in the TNNT2 gene can cause three phenotypically distinct cardiomyopathies: hypertrophic, restrictive, and dilated." (PMID 23586019, 2013). "Recently, study showed that polymorphism in intron 3 of TNNT2 significantly affected the mRNA expression pattern by skipping exon 4 during splicing in cardiomyopathy patients." (PMID 23586019, 2013). "Hypertrophic (HCM) and dilated (DCM) cardiomyopathies result from sarcomeric protein mutations, including cardiac troponin T (cTnT, TNNT2)." (PMID 18612386, 2008). "Furthermore, phenotypic rescue upon overexpression of wild-type TNNT2 suggests that this allele is amenable to a gene replacement approach aimed at restoring wild-type function in TNNT2-mutant cardiomyopathies." (PMID 42016857, 2026). "Furthermore, mutations in genes like TTN, TNNI3, and TNNT2 have been associated with a spectrum of cardiomyopathies, reflecting the complexity of genetic influences on cardiac function and structure." (PMID 38893676, 2024).
cardiomyopathy (continued). "This revealed that transcriptomic changes directly correlate with sarcomere function and can be used to predict TNNT2 variant pathogenicity, indicating that reclassification of TNNT2 variants would improve cardiomyopathy risk determination and treatment responses in patients with these variants." (PMID 35433691, 2022). "This suggests that this TNNT2 variant can result in a complex cardiomyopathy with a great diversity of morphological, functional, and clinical features that are potentially caused by different cellular mechanisms arising from other TNNT2 variants." (PMID 34977031, 2021). "However, 90% of the cardiomyopathy-causing TNNT2 variants occur in the unresolved regions, including the I79N TNNT2 variant." (PMID 34977031, 2021). "Finally, we also identified four variants of uncertain significance in cardiomyopathy-associated genes (TNNT2, PRDM16, LDB3, and SDHA) in three fetuses." (PMID 33553264, 2020). "Besides, mutations in a single sarcomere gene like cardiac troponin T (TNNT2) are sufficient to cause cardiomyopathy, and TNNT2 mutations are the most common ‘drivers’ of thin filament deficiency in both DCM and HCM." (PMID 31796423, 2019). "In patient-derived iPSC cardiomyocytes bearing a DCM-associated mutation in TNNT2, it was shown that cTnT accumulates in the nucleus and may regulate epigenetic modifications that exacerbate the pathogenesis of cardiomyopathy." (PMID 29416706, 2018). "Overall, these findings have important implications for the clinical and genetic study of families with cardiomyopathy, above all the findings of some TNNT2 mutations, which, given its demonstrated malignancy, should cause a change in the management of individuals in SCD prevention." (PMID 30393638, 2018). "Many mutations related to cardiomyopathy have been reported in TNNT2." (PMID 23674069, 2013). "Cardiomyopathies secondary to TNNT2 mutations are inherited as autosomal dominant traits." (PMID 18612386, 2008). "We determined whether TNNT2 mutations cause cardiomyopathies by altering cTnT function or quantity; whether the severity of DCM is related to the ratio of mutant to wildtype cTnT; whether Ca2+ desensitization occurs in DCM; and whether absence of cTnT impairs early embryonic cardiogenesis." (PMID 18612386, 2008). "We observed significant associations with individual cardiomyopathy genes, finding that mitral annular plane systolic excursion associated with TTN and TNNT2, and LA pump volume and RA-EF associated with MYH7." (PMID 40660250, 2025). "Seven variants (41%) were detected in genes associated with cardiomyopathies including CSRP3, LAMA4, MYH6, MYBPC3, TNNI3, TNNI3K, and TNNT2." (PMID 39272661, 2024). "There is an increased prevalence of rare variants (BAG3, LMNA, MYH7, TCAP, TNNT2, and TTN), particularly TTNtv, in adult and pediatric cancer patients with cancer therapy-induced cardiomyopathy." (PMID 39070560, 2024). "We consider the regulation of Pip4k2c, Ehmt2, Gper1, Dicer 1, Cul4b, Fyco1, Gn3l and TNNT2 in the context of doxorubicin-induced cardiomyopathy as particularly relevant." (PMID 39285385, 2024). "ARP5 expression increased with cardiomyopathy and was negatively correlated with the expression of Tnnt2 and Ttn, which were regulated by cardiac MYOCD‐MEF2." (PMID 36610028, 2023). "The function of hub genes Tnnt2 and Myh7 have all been discussed in regard to cardiomyopathy and skeletal muscle myopathy." (PMID 37888673, 2023). "These genes are associated with cardiomyopathy, familial hypertrophic, 4, or CMH4 (OMIM #115197) for MYBPC3, CMH1 (OMIM #192600) for MYH7, CMH3 (OMIM #115196) for TPM1, CMH2 (OMIM #115195) for TNNT2, and CMH7 (OMIM #613690) for TNNI3." (PMID 36555486, 2022). "In humans, a variety of cardiomyopathies are associated with mutations in all three cardiac troponin subunits (TNNT1, TNNT2, and TNNT3)." (PMID 33329019, 2020).
cardiomyopathy (continued). "Together, our results reveal the significance of OFT expression of Tnnt2 for cardiac function and demonstrate zebrafish larva as a powerful and convenient in vivo platform for studying cardiomyopathy and the relevant therapeutic strategies." (PMID 31796423, 2019). "Our findings suggest that the variants in TNNT2 and BAG3 are associated with a high propensity to life-threatening cardiomyopathy presenting from childhood and young adulthood." (PMID 28669108, 2017). "In April 2024, the ClinGen Cardiomyopathy Variant Curation Expert Panel (VCEP) adapted the ACMG/AMP criteria for eight of the sarcomeric genes (MYH7, MYBPC3, TNNI3, TNNT2, TPM1, ACTC1, MYL2, and MYL3), providing a refined framework for variant interpretation in these genes." (PMID 41357762, 2025). "A variant of uncertain significance was identified in a fourth gene, troponin T2 (TNNT2), associated with cardiomyopathy but not the cleft mitral valve, with mild mitral regurgitation seen in this case." (PMID 37626566, 2023). "Additionally, fewer cardiomyopathy-associated pathogenic mutations have been identified in TNNC1 compared to other thin filament genes, such as TNNT2 and TNNI3." (PMID 36158814, 2022). "TNNT2 is exclusively expressed in cardiac muscles, and it releases into the circulation by reflecting the extent of myocardial injury in acute coronary syndrome, myocarditis, cardiomyopathy, and anti-cancer therapy-induced cardiotoxicity." (PMID 35479276, 2022). "We identified novel DNVs in diagnostic-grade genes (RYR2, TNNT2, PTPN11, MYH7, LZR1, NKX2-5), and five cases harbouring a combination of prioritised variants, suggesting that oligogenic inheritance and genetic modifiers contribute to cardiomyopathies." (PMID 36357925, 2022). "Deletion of thin filament markers Tnnt2 and Tnni3 and thick filament marker Ttn in mice caused severe cardiomyopathy pinpointing the relevance that RYBP may function in the development of cardiomyopathy in humans as well." (PMID 32673370, 2020). "Variants in the TNNT2 gene have earlier been reported in different cardiomyopathies, hypertrophic, non-compaction and dilated cardiomyopathy." (PMID 28669108, 2017). "Notably, sarcomeric genes such as TNNI3, TNNT2, MYBPC3, and MYH7 are classically associated with HCM, but the findings obtained by the present review demonstrate their significant role in DCM as well, establishing them as shared genetic substrates between the two cardiomyopathies." (PMID 41374444, 2025). "Discordant interpretations exist for 229 variations in Hypertrophic Cardiomyopathy, with the majority of these variations located in well-known cardiomyopathy-related genes such as MYBPC3 (68 variations), MYH7 (49 variations), TNNI3 (20 variations), or TNNT2 (20 variations)." (PMID 37946154, 2023). "In the present study, loss of one allele of Tnnt2 did not cause HCM or DCM, suggesting that neither cardiomyopathy results from haploinsufficiency." (PMID 18612386, 2008).
acute coronary syndrome (58 papers, 2010 to 2025). Signs and symptoms related to acute ischemia of the myocardium secondary to coronary artery disease. "Measurement of TNNT2 is used for diagnosing acute coronary syndrome." (PMID 35479276, 2022).
myocardial ischemia (49 papers, 2009 to 2026). A disorder of cardiac function caused by insufficient blood flow to the muscle tissue of the heart. "TNNT2 is the gene that encodes Troponin-T, which is found only in heart muscle and is used clinically as a marker of cardiac ischemia." (PMID 39232179, 2024).
myocarditis (44 papers, 2010 to 2026). Myocarditis is a condition that is characterized by inflammation of the heart muscle (myocardium). "During the follow-up, only one patient who presented positive staining for TNNT2 protein developed fatal myocarditis after receiving the immune checkpoint inhibitor." (PMID 35479276, 2022).